KCNJ5 (potassium inwardly rectifying channel subfamily J member 5)
Diseases named in the same sentence as KCNJ5 in open-access papers (continued):
Sharing a sentence is not in itself a finding about the gene and the disease.
adenoma (continued). "Aldosterone-producing adenomas with CTNNB1 mutations have been reported to have higher CYP11B2 mRNA and protein (by immunohistochemistry) expression levels compared to those harboring KCNJ5 mutations." (PMID 29594118, 2018). "Given the genotype–phenotype correlations in KCNJ5-mutant adenomas (see previous sections), a subset of these tumors may harbor weak glucocorticoid function." (PMID 29594118, 2018). "We further studied the ‘enrolled group’, defined as those patients without mutated adenoma (WT group) and those with CTNNB1or KCNJ5 mutations (n = 213)." (PMID 28102204, 2017). "We postulate that in adenomas with no somatic mutations of the KCNJ5 gene, that aberrant GNRHR expression regulates aldosterone production." (PMID 27196470, 2016). "We did not observe correlations between KCNJ5 mutations and adenoma size or disease severity factors, such as lower serum potassium or higher plasma aldosterone level." (PMID 26807823, 2016). "Females with and without KCNJ5 mutations had surgery at similar ages and their adenomas were of similar size at surgery." (PMID 22848660, 2012). "However, other studies showed that the immunoreactivity of CYP11B1 was relatively low in adenomas without KCNJ5 mutations." (PMID 36950676, 2023). "Validation of expression levels of genes associated with processes of cell death and cell proliferation in an expanded sample set of 71 APAs identified a subset of genes with transcription profiles strongly correlated with adenoma diameter in KCNJ5-mutation negative APAs." (PMID 36004349, 2022). "While these findings question the ZG origin of KCNJ5-mutant adenomas, it also raises the possibility that KCNJ5-mutant tumors may arise from existing adrenal cortical nodules that undergo functional dysregulation, a hypothesis that requires further investigation." (PMID 29594118, 2018). "Therefore, it could potentially be the reason for the high aldosterone production seen in patients with KCNJ5-mutant APAs despite the low expression of CYP11B2 in the adenoma." (PMID 27777363, 2016). "Hence, patients with KCNJ5 mutations were more frequently female and diagnosed younger than patients harboring CACNA1D mutations and non-carriers; and CACNA1D mutations associated with smaller adenoma size." (PMID 26124749, 2015). "CYP11B, KCNJ5, VSNL1, CYP17A1 and Ki67 were detected by immunohistochemistry on formalin‐fixed paraffin‐embedded adrenal tissue (normal; n=2, adenoma; n=11, adenocarcinoma; n=7)." (PMID 36214464, 2022). "These tumors were no different than KCNJ5-mutant adenomas with respect to their tumor size, aldosterone levels, and age at the time of diagnosis." (PMID 29594118, 2018). "KCNJ5 and VSNL1 expression varied and was not different between adenomas and carcinomas (KCNJ5 220, versus 35,; p=0.2, VSNL1 210, versus 130,; p=0.3)." (PMID 36214464, 2022).
Hypertension (38 papers, 2013 to 2026). The presence of chronic increased pressure in the systemic arterial system. "Familial hyperaldosteronism type III results from mutations in the KCNJ5 gene, which lead to excessive aldosterone production and hypertension due to dysfunction of the GIRK4 channel in the adrenal gland." (PMID 42280146, 2026). "Our novel findings highlight the importance of understanding the molecular mechanisms underlying KCNJ5 mutations in PA and hypertension pathogenesis." (PMID 42280146, 2026). "While the presence of a KCNJ5 somatic mutation has been identified as an independent predictor of hypertension remission following unilateral adrenalectomy in patients with lateralized PA, its prevalence differs between Asian and European populations." (PMID 40033141, 2025). "Sex, BMI, duration of hypertension, KCNJ5 mutation, and cortisol co-secretion were independent predictors for complete clinical success in UPA after surgery." (PMID 38745957, 2024). "Based on the statistical results, we found that patients with uPA harboring KCNJ5 mutations were significantly younger, had smaller waistlines, a higher prevalence of hypokalemia, and shorter hypertension durations." (PMID 37614534, 2023). "A germline mutation (Thr158Ala) in KCNJ5 was subsequently found in the father and two daughters, whose huge adrenals with bilateral hyperplasia required surgical removal to control severe hypertension." (PMID 37612380, 2023). "The patients with KCNJ5 mutations were correlated with a change in baPWV even after adjusting for age, sex, and hypertension status both before and after PSM." (PMID 36950676, 2023). "APA patients with KCNJ5 somatic mutations are generally younger, female, have higher aldosterone levels, lower potassium levels, larger tumor size, and higher hypertension cure rate after adrenalectomy." (PMID 36950676, 2023). "In our previous study, after matching for age, sex, body mass index (BMI), and hypertension status, KCNJ5 mutation carriers had a higher aldosterone level, LVMI, and inappropriately excessive LVMI (ieLVMI) than non-carriers." (PMID 36950676, 2023). "In each case, possession of the KCNJ5 mutation was found to be an independent factor for remission of postoperative hypertension." (PMID 36012306, 2022). "Analysis has also been conducted using a retrospective cohort to evaluate the impact of the KCNJ5 mutation on the remission of hypertension." (PMID 36012306, 2022). "In multivariable analysis, AAC score was independently associated with KCNJ5 mutations (β=-0.168, P=0.014), age (β=0.387, P<0.001), systolic blood pressure (β=0.171, P=0.010), and number of hypertension drugs (β=0.153, P=0.024)." (PMID 35311227, 2022). "AAC score was related to several factors including KCNJ5 mutations (P<0.001), age (P<0.001), systolic blood pressure (P=0.020), duration of hypertension (P=0.001) and number of hypertension drugs (P=0.003) in univariate analysis." (PMID 35311227, 2022). "Second, the rate of residual hypertension was lower in the patients with KCNJ5 mutations after adrenalectomy." (PMID 34503121, 2021). "KCNJ5 mutation carriers were shown to have a higher likelihood of cure from hypertension after adrenalectomy." (PMID 34572353, 2021). "Some common clinical phenotypes in both Western and Asian APA patients with KCNJ5 mutations have been observed, including younger age, higher aldosterone level, lower potassium level, and higher hypertension cure rate." (PMID 34503121, 2021). "The KCNJ5 mutation carriers were younger (p < 0.001), had a shorter duration of hypertension (p = 0.018), higher DBP (p = 0.003), higher aldosterone level (p < 0.001), higher ARR (p = 0.003), and lower potassium level (p < 0.001)." (PMID 34503121, 2021). "Mutations in the the potassium channel, KCNJ5, have been recently identified as a cause of hyperaldosteronism in human hypertension." (PMID 29222092, 2018).
Hypertension (continued). "The duration of hypertension is shorter among CTNNB1 mutation carriers than KCNJ5 mutation carriers or WT APA patients (all p < 0.001)." (PMID 28102204, 2017). "The generalized additive model (GAM) smoothing plot shows the log odds ratio to predict the cure of hypertension according to chronological age, stratified by KCNJ5 mutational status." (PMID 28415786, 2017). "This strategy was successfully applied to find new genetic variants for Mendelian CVDs such as hypertension (KCNJ5, KLHL3 gene), dilated cardiomyopathy (BAG gene), or familial combined hypolipidemia (ANGPTL3 gene)." (PMID 29445720, 2017). "Therefore, further studies are needed to confirm the prognostic value of KCNJ5 mutations in predicting hypertension remission after adrenalectomy for lateralized PA in other ethnic groups." (PMID 40033141, 2025). "An association was observed between pathogenic KCNJ5 variants and ahigher prevalence in female patients, an earlier PA diagnosis, fewerelectrocardiographic alterations, and a trend towards earlier hypertension onset,echoing findings from a previous systematic review." (PMID 41196931, 2025). "In addition, patients with KCNJ5 mutations are younger, who have a shorter hypertension duration and less severe vascular remodeling." (PMID 39574955, 2024). "Due to differences in the incidence of KCNJ5 somatic mutations between Eastern and Western populations, the cure rate of hypertension post-adrenalectomy may also be affected by ethnicity." (PMID 36950676, 2023). "A set of somatic KCNJ5 mutations, which also occasionally appear in the germline – for example, Thr158Ala, Gly151Arg and Glu145Gln – cause a florid Mendelian syndrome with macroscopic adrenal hyperplasia, early-onset hypertension and hypokalaemia." (PMID 37612380, 2023). "Furthermore, the presence of the KCNJ5 somatic mutation was an independent hypertension remission predictor after unilateral adrenalectomy in patients with uPA." (PMID 37614534, 2023). "The converse is true of KCNJ5 mutations, which may explain why KCNJ5-mutant tumours are usually solitary, and hypertension is usually cured by their removal." (PMID 37612380, 2023). "In univariate analysis, aortic wall thickness at the SMA level was associated with KCNJ5 mutations (P=0.001) and the duration of hypertension (P=0.044), and aortic wall thickness at the IMA level was associated with KCNJ5 mutations (P=0.001), potassium (P=0.034) and creatinine (P=0.002) levels." (PMID 35311227, 2022). "In addition, previous studies demonstrated that KCNJ5 mutation carriers have a higher likelihood of cure from hypertension after adrenalectomy." (PMID 34572353, 2021). "In some studies, patients with KCNJ5-positive tumors have been associated with a better surgical outcome and postoperative resolution of hypertension with the administration of limited number hypertensive drugs compared to patients with wild type KCNJ5 channels." (PMID 33800142, 2021). "This implies that a younger age and shorter hypertension duration may have accounted for the lower baPWV in the patients with KCNJ5 mutations before PSM." (PMID 34503121, 2021). "Five common single nucleotide polymorphisms (SNPs) of the KCNJ5 gene (rs6590357, rs4937391, rs3740835, rs2604204, and rs11221497) were detected in patients with sporadic PA (n = 235) and essential hypertension (EH; n = 913) by the TaqMan polymerase chain reaction method." (PMID 23382865, 2013). "The possible causes of the greater decrease in PWV after surgery in KCNJ5 mutation carriers may be due to higher baseline aldosterone levels, less residual hypertension, and lower incidence of autonomous cortisol secretion compared to patients without KCNJ5 mutations." (PMID 36950676, 2023). "KCNJ5 somatic mutations have been shown to be a good prognostic predictor for the remission of hypertension after unilateral adrenalectomy in APA patients, and steroid profiling to predict mutation status may be of value to make a comprehensive plan of treatments." (PMID 36950676, 2023).
Hypertension (continued). "However, after matching for the effects of age, sex and blood pressure, APA patients who had CTNNB1 mutations had significantly higher risk of post-operative residual hypertension than either KCNJ5-mutaion carriers (OR = 18.2, p = 0.046) or WT patients (OR = 14.5, p = 0.028)." (PMID 28102204, 2017). "This study reveals that the duration of hypertension and cortisol co-secretion were independent risk factors for complete clinical remission in UPA after surgery, while KCNJ5 mutation was a protective factor." (PMID 38745957, 2024). "There were significant differences in hypertension duration, diastolic blood pressure (DBP), percentage of KCNJ5 mutation, and eGFR among the three groups." (PMID 39574955, 2024). "The observation also makes it unlikely that good outcomes in patients with KCNJ5-mutant APAs are due to earlier detection of hypertension during obstetric or contraceptive consultations." (PMID 36646800, 2023). "Germ line mutations of KCNJ5 cause familial hyperaldosteronism type 3 (FH3), which is associated with severe hyperaldosteronism and hypertension." (PMID 35723389, 2021). "Mutations in the human inwardly rectifying K channel CNJ type (KCNJ) 5 (KCNJ5) gene encoding the G-coupled inwardly rectifying K channel 4 (GIRK4) cause abnormal aldosterone secretion and hypertension." (PMID 29222092, 2018). "Even after adjustment for possible variables when compared with all those who had KCNJ5 mutations, being a CTNNB1 mutation carrier was an independent factor to predict post-operative residual hypertension [odds ratio (OR) = 18.9, p = 0.010]." (PMID 28102204, 2017). "The plot showed that APA patients who were KCNJ5-mutant carriers and aged between 37 to 60 years old, were conferred an advantage in recovering from hypertension." (PMID 28415786, 2017). "In another study, only e’ was significantly higher in KCNJ5 mutation carriers compared to non-carriers before surgery, even after matching for age, sex, and hypertension status between both groups." (PMID 36950676, 2023). "Previous studies showed that unilateral PA patients carrying KCNJ5 mutations had a better hypertension prognosis after adrenalectomy than that of those non-mutant carriers." (PMID 34440230, 2021). "After propensity score matching (PSM) for age, sex, body mass index, blood pressure, number of hypertensive medications, and hypertension duration, there were 66 patients in each group with and without KCNJ5 mutations." (PMID 34503121, 2021). "APA patients with KCNJ5 mutations have been reported to be younger, have a higher aldosterone level, lower potassium level, and higher hypertension cure rate compared to those without mutations in previous studies." (PMID 34503121, 2021). "After 1:1 PSM for age, sex, BMI, SBP, DBP, duration of hypertension, and number of hypertensive medications, there were 66 patients in each group (KCNJ5 mutation carrier group and non-carrier group)." (PMID 34503121, 2021). "The mechanism to explain KCNJ5 mutant carriers aged between 37 to 60 years old may have better hypertension prognosis is unclear." (PMID 28415786, 2017). "Compared with the KCNJ5 mutation carriers (12.5% vs. 79.3%, p < 0.001) and WT group (12.5% vs. 57.3%, p = 0.018), the CTNNB1 mutation carriers had a much lower chance of recovery from hypertension even after one-year follow-up." (PMID 28102204, 2017). "From a cohort of more than 1500 unrelated subjects referred for evaluation of genetic forms of hypertension, we identified 40 subjects diagnosed with hypertension and PA by age 10 years in whom disease-causing mutations in CYP11B2, KCNJ5, and CACNA1D were excluded." (PMID 25907736, 2015). "While germline mutations in KCNJ5 and CACNA1D were discovered following the initial identification of their somatic mutations in APAs, the discovery of the recurrent CACNA1H mutation relied entirely on brute force sequencing of patients with early severe aldosteronism and hypertension." (PMID 25907736, 2015).
Hypertension (continued). "While patients with KCNJ5-mutant APA often have severe hypertension, they are also the most likely to be cured of hypertension postsurgery." (PMID 40690719, 2025). "However, the mutational status of KCNJ5 was not a predictive factor for curing hypertension." (PMID 28415786, 2017). "Multiple regression analysis showed that male sex, higher BMI, longer duration of hypertension, cortisol co-secretion (1-mg DST>1.8 μg/dL), and absence of KCNJ5 mutation were independent predictors for complete clinical success." (PMID 38745957, 2024). "Evidence showed KCNJ5-mutant carriers were younger, had higher levels of preoperative aldosterone, more severe hypokalemia, and had a better hypertension prognosis after adrenalectomy than non-mutant carriers." (PMID 28415786, 2017). "Furthermore, the tumor size and ratio of parental hypertension were not significantly different among patients who had CTNNB1 mutations, KCNJ5 mutations or WT." (PMID 28102204, 2017). "Because of the small sample size and lack of correlations between the KCNJ5 mutation and disease-specific parameters related to APA except management of hypertension, we could not strongly recommend early diagnosis of APA based on the KCNJ5 mutation status." (PMID 26807823, 2016). "A recent study revealed lower brachial-ankle PWV (baPWV) in patients with KCNJ5 mutations compared to those without mutations before propensity score matching (PSM), but similar baPWV in both patients with and without mutations after matching for age, sex, BMI and hypertension status." (PMID 36950676, 2023).